DLX2 (distal-less homeobox 2)
Diseases named in the same sentence as DLX2 in open-access papers (continued):
Sharing a sentence is not in itself a finding about the gene and the disease.
tumor (continued). "Thus, Dlx-2 may trigger necrosis if tumor cells are under such a metabolic stress environment." (PMID 21917150, 2011). "Moreover, DLX2 drives GC malignancy by activating the PI3K/AKT pathway, a well-established regulator of EMT and tumor aggressiveness." (PMID 41244921, 2025). "In this study, we hypothesize that DLX2 promotes GC malignancy by activating the PI3K/AKT pathway to induce EMT, thereby increasing tumor proliferation, invasion, and metastasis." (PMID 41244921, 2025). "A CSRS scoring system including four CS genes (MYC, DLX2, EPHA3, and LIMK1) was constructed, which could distinguish the survival outcome, tumor microenvironment (TME) status, and ICB treatment response of patients with different CSRS score." (PMID 36106335, 2022). "Interestingly, DLX2 is induced by TGF-β, leading to the shift of TGF-β action from tumor suppression into tumor promotion." (PMID 33924205, 2021). "Moreover, the expression levels of LEP, DLX2, CLSTN2, and REG3A were significantly higher in tumor tissues than normal tissues." (PMID 33194689, 2020). "Our findings show the complexity and vitality of these tumours, shedding some light on features such their richness in connective tissue and, they point to some interesting candidate genes (i.e., DLX1, DLX2) worth further investigations that could help the pathologists in the differential diagnosis." (PMID 23947815, 2013). "In other words, in the absence of metabolic stress, Dlx-2 may promote tumor growth and progression by unknown mechanisms, but in the presence of metabolic stress, it may facilitate metabolic stress-induced necrosis by promoting mitochondrial ROS production." (PMID 21917150, 2011). "Metabolic stress-induced necrosis is driven by increased ROS production that is stimulated by Snail and Dlx-2, which mediates EMT for tumor invasion in the absence of metabolic stress." (PMID 29636841, 2018). "We did not see upregulation of reported tumour-suppressor genes, such as CDKN2A, CDKN2B and PML, and factors for neuronal differentiation, such as SMARCC1 and DLX2, in our microarray analysis." (PMID 26838672, 2016).
cancer (21 papers, 2009 to 2025). A tumor composed of atypical neoplastic, often pleomorphic cells that invade other tissues. "Future research should explore the role of DLX2 in therapy-resistant niches and its crosstalk with stromal components, such as cancer-associated fibroblasts and immune cells, to fully elucidate its impact on the TME." (PMID 41244921, 2025). "Many regulatory molecules involved in necrosis, including Snail and Dlx-2, are implicated in the metabolic reprogramming of cancer cells." (PMID 29636841, 2018). "Via the Cancer Immunome Atlas (TCIA) database, lower expression of DLX2 was also found to be associated with better IPS score of PD-1/PD-L1 blockade (p < 0.001) as well as CTLA-4 combined with PD-1/PD-L1 blockade (p < 0.001)." (PMID 36317140, 2022). "Function enrichment analysis also revealed that higher expression of DLX2 was associated with cell growth and development, Wnt signaling pathway, histone methylation, transforming growth factor β (TGF-β) pathway, and many cancers." (PMID 36317140, 2022). "During this study, we demonstrated that overexpression of transcription factor DLX2, activation of Smad2/3 signaling, and increased expression of betacellulin were observed in A549 cancer cells surviving the fractionated irradiation." (PMID 33924205, 2021). "Recently, several regulatory molecules involved in necrosis, including Snail and Dlx-2, have been shown to play important roles in the metabolic reprogramming of cancer cells." (PMID 29636841, 2018). "Many regulatory molecules that are involved in EMT, including Snail, Dlx-2, HIF-1α, STAT3, TGF-β, Wnt, and Akt, have been implicated in the metabolic reprogramming of cancer cells." (PMID 30671168, 2018). "Recently, it is regarded to play an important role in carcinogenesis, since Dlx-2 expression correlates with more advanced cancer stage and with poor prognosis in a variety of human cancer types." (PMID 29636841, 2018). "IR promotes EMT via Smad-dependent TGF-β signaling in cancer cell lines, and DLX2 is a target gene of Smad-dependent TGF-β signaling and negative feedback factor." (PMID 26799321, 2016). "In spite of these previous reports, the role of DLX2 in acquisition of CSC and EMT characteristics and its association with Smad-dependent TGF-β signaling in irradiated cancer cells have been remained elusive." (PMID 26799321, 2016). "Since elevated expression of DLX2 has been found in many malignant tumors, our results strongly support the possible involvement of DLX2 in EMT and radioresistance in many tumors." (PMID 26799321, 2016). "Here, we show that Dlx-2 is induced in cancer cells that die by necrosis in response to metabolic stress." (PMID 21917150, 2011). "In addition, a recent study showed that high expression of DLX2 was related to terminal stages of cancer and needy prognosis in patients with HCC." (PMID 31920462, 2020). "Here we investigated the role of DLX2 in association with radiation-induced epithelial to mesenchymal transition (EMT) and stem cell-like properties and its regulation by Smad2/3 signaling in irradiated A549 and MDA-MB-231 human cancer cell lines." (PMID 26799321, 2016). "Thus, we examined the expression of Dlx-2 in the cancer cell lines that undergo either necrosis or apoptosis upon GD treatment." (PMID 21917150, 2011). "Among those, we identified the known BMP-2 target genes Id1, Id3, Dlx2 and Hey1, and genes that could be functionally annotated to Wnt signaling, pathways in cancer or cytokine-cytokine receptor interaction and that have critical roles in osteogenesis." (PMID 21998639, 2011). "In particular DLX5 overexpression, together with concomitant DLX2 downregulation, could identify a subset of more aggressive cancers that would need a different treatment and a more careful follow-up." (PMID 21108812, 2010).
cancer (continued). "Moreover, we found that oxidative phosphorylation was repressed in the maxillary processes of wnt1cre; Rosa26Dlx2/- mice, in agreement with previous reports that the Dlx-2/Snail cascade is involved in glycolysis switch and mitochondrial repression in cancer cells." (PMID 35514355, 2022). "However, the role of DLX2 appears to be cancer-type dependent." (PMID 34203994, 2021). "We analyzed next whether DLX2-silencing influences cancer cell survival after irradiation." (PMID 26799321, 2016). "We determined next whether DLX2 would provide increased cancer cell survival after irradiation." (PMID 26799321, 2016). "Dlx-2, a transcriptional factor involved in embryonic development, tissue homeostasis, and the cell cycle, is important in carcinogenesis; Dlx-2 expression correlates positively with more advanced cancer stages and with poor prognosis in a variety of human cancer types." (PMID 26771232, 2016). "This study investigated the role of DLX2 in the radioresistance and CSC properties induced by IR in NSCLC cancer cells." (PMID 33924205, 2021). "EMT can regulate the metabolic reprogramming of cancer cells by regulating the many regulatory molecules involved in EMT, including Snail, Dlx-2, HIF-1α, STAT3, TGF-β, Wnt, and Akt." (PMID 30671168, 2018). "Finally, we measured levels of Dlx-2, GLS1, Snail and Snail-targeting miRNAs in human cancer tissues." (PMID 26771232, 2016). "DLX2 in turn promoted the expression of CSC and EMT-related genes resulting in the enhanced migration and invasion ability and radioresistance in A549 and MDA-MB-231 human cancer cells." (PMID 26799321, 2016). "The up-regulation and down-regulation of genes in the cancer cells could also be attributed to the activation of specific transcription factors such as ATF3, RUNX2, ERG, DLX1 (and DLX2) identified in the cancer cell transcriptomes." (PMID 20021671, 2009). "Firstly, since limited number of LUSC patients with ICI treatment was available to confirm the prognostic value of DLX2, its significant significance might be ignored, while the better ICI treatment outcome in DLX2-low patients was observed in a large sample-size of patients with other cancers." (PMID 36317140, 2022).
hematologic malignancies (3 papers, 2016 to 2022). "While several researches have proposed the association between dysregulation of DLX2 and both solid and hematological malignancies." (PMID 36317140, 2022).
infection (2 papers, 2025 to 2026). The state of being infected such as from the introduction of a foreign agent such as serum, vaccine, antigenic substance or organism. "Immunostaining on TFs revealed that both NERUOD1 and DLX2 were initially expressed in GFAP+ astrocytes at 10 days post infection." (PMID 40401537, 2025).
neurodevelopmental disorder (1 paper, 2019). A behavioral and cognitive disorder with onset during the developmental period that involves impaired or aberrant development of intellectual, motor, or social functions. "Mutations of these deleted genes have not been implicated in a neurodevelopmental disorder in prior work, although common variation at DLX1 and DLX2 has been associated with increased risk of ASD." (PMID 29463886, 2019).
DLX2 also shares sentences with these, for which no sentence is quoted: epilepsy (3 papers); gastric adenocarcinoma (3); acute lymphoblastic leukemia (2); basal cell carcinoma (1); Brachycephaly (1); central nervous system lymphomas (1); cleidocranial dysplasia (1); dental fluorosis (1); developmental delays (1); diffuse large B-cell lymphoma (1); Focal cortical dysplasia (1); graft versus host disease (1); Hodgkins lymphoma (1); Intellectual disability (1); leukemia (1); liver cancer (1); nasopharyngeal carcinoma (1); neurological disorders (1); osteoporosis (1); schizophrenia (1); systemic lupus erythematosus (1); trigonocephaly (1); urothelial carcinoma (1).